NGF (nerve growth factor)
Diseases named in the same sentence as NGF in open-access papers (continued):
Sharing a sentence is not in itself a finding about the gene and the disease.
invasive ductal carcinomas (1 paper, 2022). "A recent study also provided the first evidence of the unfavorable prognostic value of the high expression of NGF in serum-derived exomes in a cohort of 129 patients mainly affected by invasive ductal carcinoma (96.9%) undergoing to neoadjuvant chemotherapy." (PMID 36354700, 2022).
ischemia reperfusion injury (1 paper, 2021). Adverse functional, metabolic, or structural changes in ischemic tissues resulting from the restoration of blood flow to the tissue (reperfusion), including swelling; hemorrhage; necrosis; and damage from free radicals. "In animal models of ischemia-reperfusion injury, nerve remodeling is related to the expression and release of neurotrophic factors (including NGF), which can be transported to stellate ganglia through nerve bundles." (PMID 34471416, 2021).
Lafora disease (1 paper, 2014). Lafora disease (LD) is a rare, inherited, severe, progressive myoclonic epilepsy characterized by myoclonus and/or generalized seizures, visual hallucinations (partial occipital seizures), and progressive neurological decline. "The altered metabolism of NGF and BDNF could be induced or aggravated by the neurodegeneration in the brain patients with Lafora disease." (PMID 24472629, 2014). "Altered NGF and BDNF metabolism could be induced or exasperated by neurodegeneration in the brain of patients with Lafora disease." (PMID 24472629, 2014). "However, our results suggest that impairment of p75NTR signalling and altered neurotrophins levels (NGF and BDNF) could be involved in the neurodegenerative processes of Lafora disease in the cerebral cortex." (PMID 24472629, 2014).
lateral epicondylalgia (1 paper, 2025). "Several other studies have shown that injections of NGF to the neck, elbow, or masseter muscles can mimic symptoms of clinical neck pain, chronic lateral epicondylalgia, and temporomandibular disorders, respectively." (PMID 39869323, 2025).
Leber hereditary optic neuropathy (1 paper, 2018). Leber's hereditary optic neuropathy (LHON) is a mitochondrial neurodegenerative disease affecting the optic nerve and often characterized by sudden vision loss in young adult carriers. "Its efficacy as an oral photoprotector has not been studied, but its oral administration increased the expression of nerve growth factor (NGF), and it is beneficial in patients with Leber's hereditary optic neuropathy." (PMID 29998107, 2018).
Left ventricular dilatation (1 paper, 2025). Enlargement of the chamber of the left heart ventricle. "The results demonstrated that diabetic mice treated with NGF gene therapy were protected against progressive cardiac dysfunction and left ventricular dilatation." (PMID 41471293, 2025).
leiomyosarcoma (1 paper, 2022). An uncommon, aggressive malignant smooth muscle neoplasm, usually occurring in post-menopausal women. "A similar trend was also registered in leiomyosarcoma cells, suggesting that the role of NGF is dependent on the balance between its receptors." (PMID 35326486, 2022).
lepromatous leprosy (1 paper, 2018). A chronic communicable infection which is a principal or polar form of leprosy. "Immunostaining of damaged tissues using anti-NGF and anti-NGF-R antibodies revealed higher expression of NGF in patients with lepromatous leprosy and lower expression of NGF in those with the indeterminate form of the disease." (PMID 29867937, 2018).
Lipedema (1 paper, 2022). Disorder of adipose tissue characterized by symmetric and bilateral enlargement of the lower extremities due to abnormal deposition of subcutaneous fat often in obese women. "It is also possible that the altered CGRP or NGF expression identified in lipedema skin may result from underlying tissue inflammation driven by other cytokines not measured in this study." (PMID 36142221, 2022). "Lipedema abdominal skin displayed reduced Tuj-1+ neuronal cell body density, compared to healthy controls, while CGRP and NGF was significantly elevated in Stage 3 lipedema tissues." (PMID 36142221, 2022). "The expression levels of NGF and CGRP were similar within abdomen and thigh across the stages, especially this effect, strongest in Stage 3 lipedema." (PMID 36142221, 2022). "Although no marked changes in the dermal NGF expression levels between overall lipedema and control samples were observed, a stage-wise ANOVA identified a significant effect (p < 0.01)." (PMID 36142221, 2022). "Tissue biopsies from controls and patients with lipedema stages 1–3 were assessed for neuronal cell body distribution and nociceptive neuropeptides calcitonin gene-related peptide (CGRP) and nerve growth factor (NGF)." (PMID 36142221, 2022). "Dermal biopsies from (n = 11) Stages 1–3 lipedema and control (n = 10) participants were characterized for neuronal cell body and nociceptive neuropeptide calcitonin gene-related peptide (CGRP) and nerve growth factor (NGF) distribution." (PMID 36142221, 2022).
lumbar degenerative disc diseases (1 paper, 2014). "In this study, the protein levels of NGF in discs from patients with disc herniation were examined and compared with those from discs of patients with other lumbar degenerative disc diseases." (PMID 25069717, 2014).
lymphocytic leukemia (1 paper, 2026). "PC3/Tis21/BTG2 and BTG1, prototype members of the BTG/Tob family, are antiproliferative transcriptional cofactors discovered 35 years ago as genes induced by nerve growth factor and phorbol 12-myristate 13-acetate or associated with lymphocytic leukemia." (PMID 42080092, 2026).
macular edema (1 paper, 2015). "A study focusing on the association of serum proNGF/NGF imbalance with early microvascular indicators of DR such as microaneurysm formation identified by fundus photography or macular edema visualized by OCT would be informative." (PMID 25853140, 2015).
malaria (1 paper, 2014). Malaria is a serious and sometimes fatal disease caused by a parasite that commonly infects a certain type of mosquito which feeds on humans. "Thus, rosiglitazone adjunctive therapy was associated with both elevated levels of BDNF and NGF expression and maintenance of Trk-B expression in the brains of mice infected with malaria." (PMID 24603727, 2014).
mast cell disease (1 paper, 2017). "In our mouse models, the mast cell disease induced by TRKA/NGF and TRKB/BDNF is strikingly similar to human SM, particularly to WDSM." (PMID 29088753, 2017).
mast cell leukemia (1 paper, 2017). Mast cell leukemia is a malignant form of systemic mastocytosis (SM) characterized, most of the time, by the presence of circulating mast cells. "To this end, we took advantage of the human mast cell leukemia cell line HMC-1 with KIT V560G mutation and TRKA expression, but no detectable NGF by flow cytometric analysis." (PMID 29088753, 2017).
mastocytoma (1 paper, 2011). A localized tumor composed of sheets of mast cells without atypia. "A dramatic effect of NGF treatment was observed in oncogenic c-Kit (V560G c-Kit) transformed human mastocytoma cells (HMC-1 (V560G c-Kit)) which are also induced to undergo apoptosis by treatment with imatinib." (PMID 21501463, 2011).
meningioma (1 paper, 2017). A generally slow growing tumor attached to the dura mater. "EGFR signaling which has earlier been reported in context to meningiomas were also found to be perturbed along with several other growth factor mediated signaling namely FGF signaling pathway, NGF mediated signaling, PDGF signaling and signaling by insulin receptors." (PMID 28938569, 2017).
metastatic cancer (1 paper, 2022). A carcinoma which has spread from the original site of growth to another anatomic site. "Certain tumors, such as oral, prostate, or pancreatic tumors, produce nerve growth factor (NGF), which has a role in neuropathic pain in metastatic cancer, and in the development of cachexia and tumor progression." (PMID 35762045, 2022).
metastatic melanoma (1 paper, 2018). A melanoma that has spread from its primary site to another anatomic site. "We learned that the neurotrophin NGF induced Mart-1 re-expression and changes in cell behavior and gene expression of human C8161 metastatic melanoma cells." (PMID 29175861, 2018). "That is, after co-culturing C8161 metastatic melanoma cells with NGF (72 h) followed by a BrdU pulse for 2 h, we found a dramatic decrease in BrdU-positive Mart-1:GFP-positive cells compared to Mart-1:GFP-negative cells." (PMID 29175861, 2018).
motor neuron degeneration (1 paper, 2024). "In ALS, the exact role of NGF is still not entirely understood; however, there have been multiple in vivo studies showing increased NGF levels in the spinal cord and astrocytes, with the latter promoting motor neuron degeneration." (PMID 39200370, 2024).
myasthenia gravis (1 paper, 2023). Myasthenia gravis (MG) is a rare, clinically heterogeneous, autoimmune disorder of the neuromuscular junction characterized by fatigable weakness of voluntary muscles. "NGF may be also associated with the thymic pathology found in some subtypes of Myasthenia Gravis (MG) as studies have demonstrated that NGF and its receptors are overexpressed in thymic cells of patients affected by MG." (PMID 37998739, 2023).
myeloproliferative neoplasm (1 paper, 2017). A clonal hematopoietic stem cell disorder, characterized by proliferation in the bone marrow of one or more of the myeloid (i.e., granulocytic, erythroid, megakaryocytic, and mast cell) lineages. "One out of 9 mice in the TRKA alone group developed a myeloproliferative neoplasm, probably due to mild activation of TRKA by its overexpression and/or endogenous murine NGF, while no other animals with TRKA alone, NGF alone or LNGFR showed SM or other hematological malignancies." (PMID 29088753, 2017).
myotonic dystrophy type 1 (1 paper, 2012). Steinert disease, also known as myotonic dystrophy type 1, is a muscle disease characterized by myotonia and by multiorgan damage that combines various degrees of muscle weakness, arrhythmia and/or cardiac conduction disorders, cataract, endocrine damage, sleep disorders and baldness. "Furthermore, in PC12 cells expressing myotonic dystrophy type 1-associated CTG repeats, NGF treatment resulted in reduction in expression of the MT associated proteins MAP6/STOP, while NAP protects against STOP – associated deficiencies." (PMID 23272107, 2012).
nematode infection (1 paper, 2024). "The pathways including WNT/β-catenin signaling, Th1 and Th2 activation, RAR activation, NGF-stimulated transcription, IL-15 production, and IL-4, 7, 12, and 13 signaling are the top pathways that the nematode infection elicits, which could lead to eventual protection or immune evasion." (PMID 39795948, 2024).
Nephropathy (1 paper, 2013). A nonspecific term referring to disease or damage of the kidneys. "This may lead to a new direction toward the development of T1D associated nephropathy since so far the renal expression of NGF has been thought to reflect the level of glycemic control." (PMID 23358711, 2013).
nerve sheath tumors (1 paper, 2008). "The experience with NGF expression in nerve sheath tumors is much more limited, but it seems reasonable to hypothesize that NGF might be secreted by MPNST's." (PMID 18312658, 2008).
oesophageal cancer (1 paper, 2006). "There is only one study about the role of NGF in oesophageal cancer, showing that downregulation of NGF was associated with poorer tumour differentiation and advanced tumour stage." (PMID 16832412, 2006). "In oesophageal cancer, however, only one small clinical study on NGF expression has been reported, which is very different from other studies in that they showed downregulation of NGF in tumours with poorer differentiation and in advanced stage." (PMID 16832412, 2006).
ovarian endometriosis (1 paper, 2019). A non-neoplastic disorder characterized by the growth of endometrial tissue in the ovaries. "Some evidence has also revealed that nerve growth factor (NGF) and PGP9.5-immunoactive nerve fibers are expressed in ovarian endometriotic lesions and may be involved in the generation of pain in women with ovarian endometriosis." (PMID 31491902, 2019).
ovarian tumor (1 paper, 2016). "And so, we chose CAOV3 and OVCAR3 cells to ascertain the functional role of NGF/NGFRs on ovarian tumor collective migration in a relatively real 3D growth environment." (PMID 27835587, 2016).
parasitemia (1 paper, 2013). "We infected C57BL/6 mice with T cruzi (Tulahuen strain) and measured the kinetics of parasitemia (by phase-contrast microscopy), heart parasite burden (by qPCR), and cardiac NGF transcript (by qPCR)." (PMID 23437390, 2013).
periodontitis (1 paper, 2020). An acute or chronic inflammatory process that affects the tissues that surround and support the teeth. "It has been shown that proinflammatory cytokines in periodontitis suppress the TGF-β-mediated expression of NGF by downregulating TGF-β-induced Smad2/3 and p38 MAPK signaling." (PMID 32411181, 2020). "Interestingly, a negative correlation was identified between periodontitis and the NGF pathway." (PMID 32411181, 2020). "Interestingly, a negative correlation between the nerve growth factor (NGF) pathway and insulin signaling pathway was identified in periodontitis, which suggested a relationship between systemic diseases and periodontitis." (PMID 32411181, 2020).
peripheral nerve lesion (1 paper, 2015). "During the repair phase following peripheral nerve lesion, dedifferentiated Schwann cells secrete a variety of neurotrophic factors and cytokines including NGF, BDNF, NT-4/5, FGF-2, IGF-1, IL-6, and IL-1ß that support neuronal survival and regenerative growth of axons." (PMID 26635533, 2015).
peritoneal disease (1 paper, 2026). "Deep infiltrating endometriosis (DIE) appears to exhibit a more intense inflammatory profile compared to superficial peritoneal disease, including increased expression of nerve growth factor (NGF), and enhanced fibrosis and neuroangiogenesis." (PMID 41590512, 2026).
Photophobia (1 paper, 2020). Excessive sensitivity to light with the sensation of discomfort or pain in the eyes due to exposure to bright light. "The simultaneous release of nerve growth factor during this process leads to gene expression and upregulation, resulting in an excessive corneal nociceptor response, which might account for symptoms of pain, burning, and photophobia." (PMID 33005449, 2020).
pituitary adenoma (1 paper, 2021). "Although NGF receptors can be identified in various adenohypophysial cell types, the role of NGF in the neural transformation of pituitary adenoma cells has not been well understood yet." (PMID 33001343, 2021).
placental insufficiency (1 paper, 2022). Failure of the placenta to deliver an adequate supply of nutrients and oxygen to the fetus. "Despite the low number of samples, the reduced expression of NGF in the allantois and the reduced expression of BDNF in the amnion seems to characterize the fetal membranes of mares with placental insufficiency that delivered foals affected by NE." (PMID 36136675, 2022).
POEMS syndrome (1 paper, 2024). POEMS syndrome is a paraneoplastic syndrome characterized by polyradiculoneuropathy (P), organomegaly (O), endocrinopathy (E), clonal plasma cell disorder (M), and skin changes (S). "This study evaluated the usefulness of EuroFlow-NGF-based MFC in detecting clonal PCs in POEMS syndrome in an era when highly sensitive EuroFlow-NGF is widely used for MRD assessment in MM." (PMID 38710832, 2024). "In this study, we aimed to verify the usefulness of EuroFlow-NGF-based multiparameter flow cytometry (MFC) in POEMS syndrome and explore suitable gating strategies to improve the diagnostic accuracy of POEMS syndrome." (PMID 38710832, 2024). "We employed EuroFlow-NGF-based single-tube eight-color multiparameter flow cytometry (MM-flow) and established a new gating strategy (POEMS-flow) to detect the monoclonal PCs in POEMS syndrome, gating CD38 broadly from dim to bright and CD45 narrowly from negative to dim compared to MM-flow." (PMID 38710832, 2024). "MM-flow was established based on EuroFlow-NGF for MRD assessment in MM14 and was not designed for detecting clonal PCs in POEMS syndrome." (PMID 38710832, 2024). "Conclusively, this study evaluated the sensitivity of EuroFlow-NGF-based MFC in detecting clonal PCs in POEMS syndrome and demonstrated the usefulness of the optimized POEMS-flow, gating CD38 broadly from dim to bright and CD45 narrowly from negative to dim compared to EuroFlow-NGF-based MFC." (PMID 38710832, 2024).
polyneuropathy (1 paper, 2016). A disease or disorder affecting more than one nerve. "Direct gene transfer of NGF into diabetic rat hearts improved cardiac sensory innervation and recombinant NGF has been shown to be safe when administered to diabetic patients with polyneuropathy." (PMID 27590099, 2016).
post-traumatic stress disorder (1 paper, 2023). An anxiety disorder precipitated by an experience of intense fear or horror while exposed to a traumatic (especially life-threatening) event. "NGF: nerve growth factor; NE: norepinephrine; PTSD: post-traumatic stress disorder." (PMID 36949968, 2023).
premature ovarian failure (1 paper, 2020). "In conclusion, CUMS may affect ovarian function and contribute to premature ovarian failure through NGF and its receptor-mediated signaling pathway." (PMID 32685448, 2020).
psoriatic arthritis (1 paper, 2023). Joint inflammation associated with psoriasis. "Two panels of biomarkers distinguishing psoriatic arthritis from osteroarthritis were suggested: (a) COMP, resistin, NGF (nerve growth factor), MCP-1 (monocyte chemoattractant protein-1) and (b) COMP, aggrecan." (PMID 37298045, 2023).
psychological distress (1 paper, 2020). "BDNF and NGF concentrations correlated to levels of psychological distress (p < 0.0005)." (PMID 32842964, 2020).
pulmonary sarcoidosis (1 paper, 2010). Sarcoidosis affecting the lung parenchyma. "While knowing that NGF is elevated in bronchoalveolar lavage fluid (BALF) of patients with pulmonary sarcoidosis, less is known about the neurotrophins BDNF and NT-3." (PMID 21059230, 2010). "In support of this, we have recently reported enhanced NGF levels in the airways of patients with pulmonary sarcoidosis." (PMID 21059230, 2010). "The present study provides evidence for increased levels of the neurotrophins NT-3 and NGF locally in the airways of patients with pulmonary sarcoidosis as compared to healthy individuals." (PMID 21059230, 2010). "In conclusion, the present study describes that the neurotrophins NGF, BDNF and NT-3 are expressed in sarcoid granulomas in the airways and that enhanced levels of NGF and NT-3 are found in bronchoalveolar lavage fluid of patients with pulmonary sarcoidosis as compared to healthy individuals." (PMID 21059230, 2010). "The aim of the present study was to compare the concentrations of the neurotrophins NGF, BDNF and NT-3 in BALF of patients with newly diagnosed pulmonary sarcoidosis with those of healthy controls." (PMID 21059230, 2010). "The concentrations of NGF, BDNF and NT-3 in bronchoalveolar lavage fluid (BALF) of 41 patients with newly diagnosed pulmonary sarcoidosis and 27 healthy controls were determined with ELISA." (PMID 21059230, 2010). "This indicates that besides NGF and NT-3, BDNF could be a messenger molecule of relevance in pulmonary sarcoidosis." (PMID 21059230, 2010).
pulpitis (1 paper, 2022). Inflammation of the dental pulp. "In pulpitis, NGF is continuously upregulated to increase the density of nerve fibers." (PMID 36555133, 2022). "Moreover, the level of NGF would increase in pulpitis to accelerate the release of neuropeptides such as SP and CGRP, resulting in pain." (PMID 36555133, 2022).
rectal tumors (1 paper, 2021). "Moreover, overexpression of NGF in the colon epithelium, using a Villin-Cre: R26-NGF mouse line, resulted in the development of more and larger rectal tumors upon chemical (AOM/DSS) tumor induction, indicating that a similar process could take place in CRC." (PMID 33466373, 2021).